OLFM2 (olfactomedin 2)
Description:
Involved in transforming growth factor beta (TGF-beta)- induced smooth muscle differentiation. TGF-beta induces expression and translocation of OLFM2 to the nucleus where it binds to SRF, causing its dissociation from the transcriptional repressor HEY2/HERP1 and facilitating binding of SRF to target genes. Plays a role in AMPAR complex organization (By similarity). Is a regulator of vascular smooth-muscle cell (SMC) phenotypic switching, that acts by promoting RUNX2 and inhibiting MYOCD binding to SRF. SMC phenotypic switching is the process through which vascular SMCs undergo transition between a quiescent contractile phenotype and a proliferative synthetic phenotype in response to pathological stimuli. SMC phenotypic plasticity is essential for vascular development and remodeling (By similarity).
Synonyms: NOE2; OlfC; NOELIN2; NOELIN2_V1
Tractability: Antibody: UniProt places it where antibodies can reach, with high confidence; its Gene Ontology location is reachable by antibodies, with high confidence; UniProt predicts a signal peptide or a membrane-spanning region. PROTAC: ubiquitination databases record sites on it.
Gene: Protein-coding gene on chromosome 19 (9,853,718 to 9,936,558, reverse strand). Ensembl gene ENSG00000105088.
Subcellular location: Secreted; Synapse; Membrane; Nucleus; Cytoplasm
Subcellular location (Human Protein Atlas): Nucleoplasm; Predicted to be secreted
Gene Ontology:
Molecular function: protein binding
Biological process: positive regulation of smooth muscle cell differentiation; protein secretion; regulation of vascular associated smooth muscle cell dedifferentiation; signal transduction
Cellular component: cytoplasm; extracellular region; nucleoplasm; nucleus; AMPA glutamate receptor complex; membrane; synapse
Genetic constraint (gnomAD): Loss-of-function variants: 20 observed, 39.5 expected, observed/expected ratio (o/e) 0.51, 90% interval 0.35 to 0.74. The upper end of that interval is the gene's LOEUF score, 0.74, which puts it in group 3 of 6, group 1 being the genes least tolerant of losing a copy. Missense variants: 416 observed, 646.43 expected, observed/expected ratio (o/e) 0.64, 90% interval 0.59 to 0.7. Synonymous variants: 268 observed, 277.5 expected, observed/expected ratio (o/e) 0.97, 90% interval 0.87 to 1.07.
Homologues: Orthologues: chimpanzee OLFM2 (97% identical), guinea pig OLFM2 (96% identical), macaque OLFM2 (96% identical), pig OLFM2 (95% identical), dog OLFM2 (95% identical), rabbit OLFM2 (95% identical), rat Olfm2 (95% identical), mouse Olfm2 (95% identical), tropical clawed frog olfm2 (79% identical), zebrafish olfm2a (76% identical), zebrafish olfm2b (53% identical). Paralogues in human: OLFM3 (61% identical), OLFM1 (57% identical), OLFML2A (28% identical), MYOC (27% identical), OLFML2B (27% identical), OLFM4 (25% identical), GLDN (21% identical), OLFML1 (20% identical), OLFML3 (19% identical).
Diseases named in the same sentence as OLFM2 in open-access papers:
OLFM2 is named in the same sentence as 18 diseases in open-access papers, as found by Europe PMC text mining. Sharing a sentence is not in itself a finding about the gene and the disease. The quoted sentences say what the papers report.
Obesity (3 papers, 2022 to 2023). Accumulation of substantial excess body fat. "Thanks to this study, we were able to evaluate the potential role of OLFM2 in adipose tissue in obesity-associated NAFLD." (PMID 36982296, 2023). "Olfactomedin 2 (OLFM2) is a secreted glycoprotein related to the regulation of lipid metabolism, insulin resistance, and obesity that has been implicated in different diseases, such as ocular glaucoma and hepatocellular carcinoma." (PMID 36982296, 2023). "Therefore, in our previous study, we evaluated the potential role of hepatic OLFM2 in obesity-associated NAFLD." (PMID 36982296, 2023). "Therefore, OLFM2 in liver tissues seems to play a role in NAFLD progression in subjects with obesity, but further studies are needed in this field." (PMID 35806447, 2022). "First, we determined the relative mRNA expression of OLFM2 in VAT and SAT in the presence of obesity (BMI < 25 kg/m2 or BMI ≥ 40 kg/m2)." (PMID 36982296, 2023). "In this sense, given that OLFMs are strongly linked to cellular processes and have been related to some disorders, such as obesity and hepatocarcinoma (HCC), among others, we wanted to evaluate the possible roles of OLFM2 and OLFM4 in NAFLD pathogenesis." (PMID 35806447, 2022).
Anxiety (2 papers, 2018 to 2020). Intense feelings of nervousness, tension, or panic often arise in response to interpersonal stresses. "In contrast to Olfm1, genetic targeting of Olfm2 did not result in gross abnormalities but mutant mice presented with abnormal locomotor coordination, reduced exploration and anxiety-related behavior." (PMID 30093905, 2018).
colorectal cancer (2 papers, 2024). A primary or metastatic malignant neoplasm that affects the colon or rectum. "Olfactomedin 2 (OLFM2), a glycoprotein that is associated with cell adhesion and differentiation, is reported to be elevated in colorectal cancer and can promote the EMT and invasion of cancer cells." (PMID 39092293, 2024). "Therefore, based on these results, we determined that OLFM2 can promote colorectal cancer EMT, migration, and invasion through the TGF-β/Smad signaling pathway." (PMID 38350902, 2024). "Although OLFM2 has been seldom reported in other tumors, its mechanisms in colorectal cancer metastasis and growth remain unknown." (PMID 38350902, 2024). "Following the collection of colorectal cancer (CRC) tissue samples, we conducted qRT-PCR and western blotting analyses on eight pairs of tissue specimens to examine the expression of OLFM2 mRNA and protein." (PMID 38350902, 2024).
Insulin resistance (2 papers, 2023 to 2024). Increased resistance towards insulin, that is, diminished effectiveness of insulin in reducing blood glucose levels. "For example, the genetic ablation of olfactomedin 2 (OLFM2), a secretory glycoprotein, reduces food intake, increases brown adipose tissue thermogenesis, and improves insulin resistance; conversely, its overexpression in the lateral hypothalamic area (LHA) has opposite effects." (PMID 39876968, 2024).
steatosis (2 papers, 2022 to 2023). Increased lipid within the cytoplasm of cells. "In summary, we have carried out a novel study showing that the hepatic expression of OLFM2 seems to increase as NAFLD progresses, and this protein seems to be associated with NASH and with a severe steatosis pattern in NAFLD patients." (PMID 35806447, 2022). "Our results showed that OLFM2 hepatic mRNA was higher in NASH, in advanced degrees of steatosis and in the presence of lobular inflammation." (PMID 35806447, 2022). "We found that OLFM2 expression was higher in subjects with mild and moderate steatosis than in those without it." (PMID 36982296, 2023). "Specifically, OLFM2 expression in SAT was increased in mild and moderate degrees of steatosis in comparison to the absence of it." (PMID 36982296, 2023). "Moreover, OLFM2 expression in SAT was increased in mild and moderate degrees of steatosis in comparison to the absence of it." (PMID 36982296, 2023).
colon cancer (1 paper, 2024). "We discovered that OLFM2 knockdown inhibited migration and invasion of colon cancer cells." (PMID 38350902, 2024). "Conversely, when OLFM2 is knocked down in cells SW480 and SW620, there is an increase in E-cadherin expression and a decrease in N-cadherin and Vimentin expression.These findings indicate that OLFM2 plays an important role in promoting EMT in colon cancer cells." (PMID 38350902, 2024). "In our study, we verified the role of OLFM2 in colon cancer cells through in vitro experiments." (PMID 38350902, 2024).
hepatic disease (1 paper, 2023). "We conducted a study using liver biopsies, and we found increasing relative OLFM2 mRNA expression as hepatic disease became more severe, suggesting a potential key role of OLFM2 in the progression of NAFLD." (PMID 36982296, 2023).
morbid obesity (1 paper, 2022). An excess of body weight, normally defined as an individual with a body mass index greater than 35 or a body weight greater than one hundred percent of ideal body weight. "Thus, the current study aimed to analyse OLFM2 mRNA expression in liver biopsies and OLFM4 mRNA expression in jejunum samples in a well-established cohort of women with morbid obesity (MO) with different NAFLD grades to explore the role of OLFMs in the pathogenesis of NAFLD." (PMID 35806447, 2022).
open-angle glaucoma (1 paper, 2019). Chronic outflow obstruction of the eye's drainage canals that can lead to increased internal eye pressure and optic nerve damage. "A variant in another OLF family member, OLFM2, has been associated with human open angle glaucoma in a small number of Japanese patients (rs779032127; p.Arg144Gln) and identified as contributing to eye development." (PMID 30696701, 2019).
cancer (7 papers, 2016 to 2025). A tumor composed of atypical neoplastic, often pleomorphic cells that invade other tissues. "From our best research, HOXC6, SLC2A4, VIP, CD1A, STC2, and OLFM2 are related to cancer progression." (PMID 35711425, 2022). "We also found within the most altered nodes, genes that have not been previously reported in the context of TNBC but have been reported in other cancer types, for example, the Microtubule Actin Crosslinking Factor 1 (MACF1) in chromosome 1, and olfactomedin 2 (OLFM2) in chromosome 19." (PMID 40688355, 2025). "Although OLFM2 is involved in the regulation of the energy metabolism and OLFM4 is an important player in inflammation, innate immunity and cancer, the role of OLFMs in NAFLD-related intestinal dysbiosis remains unknown." (PMID 35806447, 2022). "The function of OLFM2 in cancer is not thoroughly elucidated." (PMID 27096627, 2016).
tumor (3 papers, 2020 to 2024). "The mRNA expression of OLFM2 was significantly higher in the tumor tissue." (PMID 38350902, 2024). "As a member of the containing olfactomedin domains protein family, olfactomedin 2 (OLFM2) may play a role in tumor metastasis." (PMID 38350902, 2024). "Interestingly, olfactomedin 2 (OLFM2) was found to be significantly upregulated in all tumor tissues from the SSA/DA treated group." (PMID 33680922, 2020). "OLFM2, promoting nerve growth, may be tumor invasion and metastasis." (PMID 37702857, 2023).
OLFM2 also shares sentences with these, for which no sentence is quoted: Anosmia (1 paper); COVID-19 (1); hepatocellular carcinoma (1); hyperlipidemia (1); myopathy (1); Nonalcoholic Fatty Liver Disease (1); pituitary tumor (1).